TBK1 (TANK binding kinase 1)
Diseases named in the same sentence as TBK1 in open-access papers (continued):
Sharing a sentence is not in itself a finding about the gene and the disease.
bacterial infection (20 papers, 2015 to 2025). "Recently we demonstrated that macrophages isolated from TG2 knockout mice displayed an upregulation of the cGAS/STING/TBK1 pathway, the main innate immunity routes involved in the early defence against bacterial infections." (PMID 36923406, 2023). "A similar role for TBK1 has been shown for Listeria monocytogenes, Mycobacterium tuberculosis and Streptococcus pyogenes, suggesting that TBK1 plays an essential role in restricting bacterial infections following cellular membrane rupture." (PMID 35857795, 2022). "In response to an invasive bacterial infection, TBK1 phosphorylates NDP52 and contributes to autophagic maturation and the elimination of mycobacteria." (PMID 35395857, 2022). "Here, we show that bacterial infection increases Ca2+ levels to activate TBK1 for xenophagy via the Ca2+-binding protein TBC1 domain family member 9 (TBC1D9)." (PMID 32034138, 2020). "TBK1 has been shown to play an important role in autophagy activation during cytosolic bacterial infection." (PMID 28529930, 2017). "TBK1 is essential for cell‐autonomous immunity against both viral and bacterial infections." (PMID 27370208, 2016). "Interestingly, the same Serine residue of Optn is phosphorylated by TBK1, and this phosphorylation is essential for Optn to function in the autophagy triggered by bacterial infection and in the antiviral innate immune responses (and this study)." (PMID 25923723, 2015). "TANK-binding kinase-1 (TBK1), an integral component of Type I interferon induction by microbial infection, is both important for autophagic maturation by coordinating assembly and function of the autophagic machinery and protection of vacuolar integrity during intracellular bacterial infection." (PMID 37771590, 2023). "Moreover, bacterial infection can also lead to TBK1 degradation, as shown for Shigella species." (PMID 36936901, 2023). "TBK1 has been shown to phosphorylate and activate IRF3/7 in response to viral and bacterial infections, which in turn drives a type I IFN response." (PMID 39415484, 2025). "Increases in cytosolic DNA from mitochondrial stress, viral and bacterial infections or damaged cells activate the cyclic GMP-AMP synthase (cGAS)-stimulator of interferon genes (STING) and TANK-binding kinase 1 (TBK1) pathway." (PMID 41432900, 2025). "During bacterial infection, phosphorylation of Serine 403 in the UBA domain of p62 by TBK-1 increases p62’s affinity for polyubiquitinated proteins and protein aggregates resulting in activation of the autophagic machinery and autophagic clearance." (PMID 37771590, 2023). "During intracellular bacterial infection, autophagy receptor NDP52 recognizes Ub-coated bacteria and recruits the adaptor proteins NAP1 and TBKBP1 to activate TBK1." (PMID 35395857, 2022). "PTK2B participates in the innate immune response through interaction with IkappaB kinase β (IKKβ) and TANK-binding kinase 1 (TBK 1), and is critical for neutrophil degranulation and host defense against bacterial infection." (PMID 31447828, 2019). "Some studies suggest that up to 70% of the TBK1 activity is the result of its interaction with the adaptor protein OPTN, while other studies have reported that TBK1 regulates the autophagy receptors OPTN and p62 during bacterial infection by phosphorylating the UBAN domain on these proteins." (PMID 34800171, 2022). "In contrast to the mRNA levels, the bacterial infection did not influence the protein levels of STING, TBK1, or IRF3 from 1 to 24 hpi." (PMID 33806598, 2021). "Knocking down BCL10 led to higher transcriptional levels of STING and TBK1, but not of IRF3 upon the bacterial infection." (PMID 33806598, 2021). "S. aureus infection influenced phosphorylation of TBK1 and IRF3 rather than protein levels of TBK1 and IRF3, indicating that the bacterial infection initiates IFN-β signaling via controlling the activities of these two proteins by posttranslational modification." (PMID 33806598, 2021).
metabolic disease (13 papers, 2020 to 2025). A congenital disorder (due to inherited enzyme abnormality) or acquired (due to failure of a metabolically important organ) disorder resulting from an abnormal metabolic process. "Emerging evidence suggests that TBK1 is a key node in regulating the potential connection between metabolism and inflammatory response in metabolic diseases." (PMID 40076567, 2025). "The STING/TBK1 pathway, a classical innate immune signaling pathway, has recently been shown to play a critical role in the inflammatory response of metabolic diseases." (PMID 39224584, 2024). "Additionally, the SCAP/SREBP/STING/TBK1 pathway can activate NF-κB in metabolic diseases and promote the expression of related inflammatory factors." (PMID 39224584, 2024). "Myeloid-specific Tbk1 knockout mice (My-Tbk1−/−) spontaneously developed adipose hypertrophy and metabolic disorders in old age due to the increased M1 macrophage infiltration and proinflammatory cytokine production (such as IL-6, TNF-α, and IL-1) in adipose tissue." (PMID 35395857, 2022). "As a dual inhibitor of TBK1 and IKK, AML has represented splendid curative effects that can even reverse the severity of NAFLD, and the TBK1-specific knockout in obese mice also brings about amelioration on metabolic disorders including lipid accumulation and inflammation." (PMID 35115947, 2021). "As TBK1 and mTOR contribute to tumorigenesis and metabolic disorders, these kinases may work together in a direct manner in a variety of physiological and pathological settings." (PMID 34245780, 2021). "Finally, we discuss the potential of a TBK1/IKKε inhibitor as a new therapy for metabolic diseases." (PMID 33193441, 2020). "The results revealed that TBK1 did not affect metabolic disorders in db/db mice, which might be related to the particularity of the model." (PMID 39030571, 2024).
neurological disorders (7 papers, 2019 to 2025). "We targeted the TBK1 ortholog in zebrafish, an optimal vertebrate model for investigating genetic defects in neurological disorders." (PMID 40075110, 2025). "Increasing studies have provided evidence of the regulatory role of STING/TBK1/IRF3 signaling in various neurological diseases." (PMID 35936778, 2022). "TBK1, OPTN, p97, and other factors involved in selective autophagy are mutated in a variety of neurological disorders such as ALS and FTD." (PMID 34585663, 2021). "From the perspective of neurological diseases, RAB7a missense mutations underlie the inherited peripheral neuropathy, Charcot-Marie-Tooth type 2B (CMT2B), while TBK1 mutations are associated with ALS." (PMID 30857122, 2019). "It is assumed that the development of these neurological diseases is due to impaired fusion of autophagosomes with lysosomes (inhibition of the NF-kB signaling pathway is enhanced), but the mutant TBK1, OPTN, and SQSTM1 genes also contribute to the pathogenesis." (PMID 39403278, 2024). "Many genes play an important role, with TARDBP, SQSTM1, VCP, FUS, TBK1, CHCHD10, and most importantly, C9orf72 being critical genetic players in these neurological disorders." (PMID 33805659, 2021). "TARDBP, SQSTM1, VCP, FUS, TBK1, CHCHD10, and most importantly C9orf72, are the critical genetic players in these neurological disorders." (PMID 32116499, 2020).
infectious disease (5 papers, 2015 to 2024). A disorder directly resulting from the presence and activity of a microbial, viral, or parasitic agent in humans. "IRF3 can be phosphorylated by TANK-binding kinase-1 (TBK1) to participate in STING-mediated inflammatory and immune responses and facilitate the progression of inflammatory and infectious diseases by regulating the transcription of interferons and inflammatory factors." (PMID 38671352, 2024). "In a recent report, an ethanol extract of Dryopteris crassirhizoma displays strong anti-inflammatory activity by suppressing ERK/AP-1 and TBK1/IRF3 pathways, which contribute to its major ethno-pharmacological role as an anti-inflammatory and anti-infectious disease remedy." (PMID 26136733, 2015). "In infectious diseases, the common endpoint is the activation of shared signaling pathways: nuclear factor kappa B (NF-κB)signaling, inflammasome signaling, mitogen-activatedprotein kinase (MAPK) signaling and TANK-binding kinase 1—interferon regulatory factor 3 (TBK1–IRF-3)signaling." (PMID 36675530, 2023).
inflammation (2 papers, 2020 to 2024). Aberrant reaction of the microcirculation characterized by movement of fluid and leukocytes from the blood into extravascular tissues. "In endothelial inflammation, cytosolic mtDNA activates cGAS, which induces the activation of TANK-binding kinase 1 (TBK1) and the phosphorylation of the transcription factor interferon regulatory factor 3 (IRF3), which are involved in vascular inflammation and destruction." (PMID 33115500, 2020).
kidney (2 papers, 2019 to 2022). "Consistently, intranasal and oral administration of amlexanox, a TBK1 inhibitor, decreased cGAMP-induced lung allergic inflammation." (PMID 31616416, 2019). "Moreover, inhibition of TBK1/IKKε with amlexanox, and IFNAR targeting, may protect from tubulointerstitial kidney injury." (PMID 36386242, 2022).
overlap syndrome (2 papers, 2019 to 2021). "Only one other case of familial CBS–PNFA overlap syndrome has been reported in the literature thus far, carrying a frameshift mutation (p.Thr156ArgfsX6) affecting the kinase domain of TBK1." (PMID 31160356, 2019). "Here, we describe the presence of a novel TBK1 mutation in a patient who presented clinically with a CBS–PNFA overlap syndrome, radiologically with asymmetric frontal lobe atrophy, and with FTLD–TDP type A pathology at postmortem examination of brain tissue." (PMID 31160356, 2019). "PPA-ALS, particularly svPPA-ALS is an uncommon phenotype, and this finding suggests a role for TBK1 in the development of this overlap syndrome." (PMID 32980182, 2021).
cardiac diseases (1 paper, 2022). "In addition to innate immunity, TBK1 plays a critical role in cardiac diseases." (PMID 35743792, 2022).
epithelial carcinoma (1 paper, 2014). "In alveolar type II epithelial carcinoma cell line, regulation of E-cadherin expression is partly controlled by Tank-binding kinase-1 (TBK1), inhibitor κB (IκB) kinase-related kinase, through activating NF-κB." (PMID 25197668, 2014).
TBK1 also shares sentences with these, for which no sentence is quoted: aphthous ulcers (4 papers); fibrosis (4); Hypertension (3); liposarcoma (3); multiple sclerosis (3); pancreatic ductal adenocarcinoma (3); allergic rhinitis (2); colon adenocarcinoma (2); corticobasal syndrome (2); dyslipidemia (2); Myocardial fibrosis (2); myocardial infarction (2); ocular toxoplasmosis (2); pulmonary hypertension (2); squamous cell carcinoma (2); stomach adenocarcinoma (2); systemic sclerosis (2); ulcer (2); vasculitis (2); viral disease (2); acute disseminated encephalomyelitis (1); acute kidney injury (1); acute respiratory distress syndrome (1); Adult onset (1); adult T-cell leukemia (1); age (1); Aicardi–Goutières syndrome (1); anemia (1); aneurysm (1); Anxiety (1).
A further 74 diseases each share a sentence with TBK1 in 1 paper.